ENSG00000278592
Gene: Miscellaneous RNA gene on chromosome 7 (27,187,819 to 27,188,021, forward strand). Ensembl gene ENSG00000278592.
Gene Ontology:
Biological process: negative regulation of gene expression